CCND1 (cyclin D1)
Diseases named in the same sentence as CCND1 in open-access papers (continued):
Sharing a sentence is not in itself a finding about the gene and the disease.
breast cancer (continued). "Six genes have been reported to contribute to about 44% of driver mutations in breast cancer (copy number increase or amplicons): MYC, FGFR1 (Chromosome 8); CCND1 (Chromosome 11); HER2, TOP2A (Chromosome 17); and ZNF217 (Chromosome 20)." (PMID 26008969, 2015). "The activity of the cyclin D1 reporter was reduced in response to retinoic acid in breast cancer cells independently of β-catenin/TCF signaling." (PMID 25806093, 2015). "The cyclin D1 gene is amplified or overexpressed in up to half of human breast cancers and its mammary-targeted overexpression induces mammary tumorigenesis in mice." (PMID 25940700, 2015). "Tunicamycin treatment resulted in concentration-dependent increase of p27 and decrease of cyclin D1 in all three breast cancer cells." (PMID 26498681, 2015). "We initiated the following study to directly test the oncogenic potential of catalytically inactive cyclin D1 in an in vivo mouse model that is relevant to breast cancer." (PMID 25940700, 2015). "Determining how let-7 interacts with cyclin D1 in breast cancer will definitely help us to understand the mechanisms of miRNAs regulated cell biology." (PMID 25702703, 2015). "Nuclear EGFR binds to the cyclin D1 promoter region and upregulates cyclin D1 expression to promote breast cancer cell cycle progression." (PMID 25997448, 2015). "Our findings are in fact in agreement with a previous report that rapamycin induces GSK3-dependent degradation of cyclin D1 in human breast cancer cell lines." (PMID 25797247, 2015). "Recent studies have shown that cyclin D1 interacts with and regulates FLNa expression in migrating breast cancer cells." (PMID 26009991, 2015). "Cyclin D1 is a key regulator of cell cycle progression, it also stimulates development of many tumors, including breast cancer." (PMID 26404249, 2015). "On the other hand, a reduction in PHD1 levels in breast cancer can hinder tumor growth due to the accumulation of FOXO3a and consequent suppression of cyclin D1 eventually leading to a decreased proliferation." (PMID 26290450, 2015). "Breast cancer cells treated with leptin and honokiol were examined for the expression of Cyclin D1 as a functional control." (PMID 26359358, 2015). "Previous study also found that Pak1 regulates prolactin mediated cyclin D1 promoter activity in breast cancer." (PMID 26218748, 2015). "Our previous studies suggest that KLF5 promotes breast cancer cell proliferation by regulating a number of target genes, such as p21, p27, Cyclin D1, FGF-BP and mPGES1." (PMID 26079537, 2015). "We further used pooled samples to carry out DNA FISH for six genes previously reported to contribute to driver mutations in breast cancer: MYC, FGFR1, CCND1, HER2, TOP2A, and ZNF217." (PMID 26008969, 2015). "CCND1 focal amplification was observed in samples from patients with breast cancer, melanoma and ovarian cancer." (PMID 25889064, 2015). "For example, cyclin D1 gene is over-expressed in 40% of human breast cancers, and high cyclin D1 expression levels correlate with the low survival probability for patients with lung cancer." (PMID 26121043, 2015). "Overexpression of cyclin D1 has been detected in numerous types of cancers, including cancers of the breast, lung and prostate and has been considered as an oncogenic mechanism in hormone-refractory metastatic prostate cancer to the bone." (PMID 26447757, 2015). "The genetic deletion of EZH2 results in the down-regulation of cyclin D1 in breast cancer and in the up-regulation of p21 in ovarian cancer, causing cell cycle arrest at the G1/S phase." (PMID 26452129, 2015). "We next examined the expression of cell-cycle regulators, such as cyclin D1 and cyclin dependent kinase inhibitor p27, which are essential for G1/S phase progression, in breast cancer cells treated with trastuzumab." (PMID 26498681, 2015). "Cyclin D1 is overexpressed at the protein level in up to 50% of all primary breast cancers, in part due to amplification of the cyclin D1 gene, CCND1." (PMID 25925673, 2015).
breast cancer (continued). "Breast cancers overexpressing cyclin D1 that are wild type for pRb have relatively normal proliferation rates, in contrast to those caused by genetic inactivation of pRb, which show significantly increased proliferation rates." (PMID 25940700, 2015). "It has been reported that cyclin D1 is direct targets of miR-206 in 3T3-L1 cells and HeLa cells, and over-expression of cyclin D1 promoted of breast cancer and A549 cells proliferation." (PMID 26325180, 2015). "The mRNA and protein levels of cyclin D1 have been found to be upregulated in more than 50% of the breast cancers and cyclin D1 represents one of the most commonly overexpressed proteins in this cancer." (PMID 26703530, 2015). "In breast cancer, cyclin D1 is known to act as an oncogene, and its main role has been in the regulation of proliferation." (PMID 25837691, 2015). "Cyclin D1 is a well-established human oncogene, which is over-expressed in lung cancer, breast cancer, melanoma and pancreatic cancer." (PMID 26023733, 2015). "Cyclin D1 is an important molecular driver of human breast cancer but better understanding of its oncogenic mechanisms is needed, especially to enhance efforts in targeted therapeutics." (PMID 25940700, 2015). "In breast cancer, PTEN coordinates G1 cell-cycle arrest by down regulating the cyclin D1 protein and increasing p27 expression, causing reduced cell growth and increased apoptosis." (PMID 26220712, 2015). "The cooperative functions of β-catenin and cyclin D1 in mammary gland development has been established, and their involvement in breast cancer development have also been shown." (PMID 26404249, 2015). "γ-secretase mediated downregulation of Notch signaling followed by reduction in Notch1 downstream products like Hes1 and cyclin D1 by 6-shogaol thus explain its efficacy in breast cancer spheroid cells." (PMID 26355461, 2015). "AGR2 can regulate breast cancer cells growth and survival by modulating Survivin, C-myc, and Cyclin D1." (PMID 25871396, 2015). "Previous studies showed that Cyclin D1 and D3 are overexpressed in human breast cancer cell lines and primary invasive breast cancers and Cyclin D3 frequently exceeded the expression of Cyclin D1 in ErbB2-positive cases." (PMID 26412984, 2015). "Overexpressed cyclin D1 was found in 50 to 70% breast cancers while CCND1 amplification, cyclin D1 gene was found in 15 to 20% breast cancer." (PMID 26592552, 2015). "The Small cell fraction also showed copy number increases in six target genes (FGFR1, Myc, CCND1, HER2, TOP2A and ZNF217) associated with breast cancer." (PMID 26008969, 2015). "More recently, a conditional knockout approach showed that cyclin D1 does represent a therapeutic target in Her2-positive breast cancer." (PMID 25223380, 2014). "Specifically, Six1 and EYA1 upregulated cyclin D; In contrast, DACH1 acted as an antagonist of cyclin D1 in breast cancer." (PMID 25322986, 2014). "We have shown that HS-133 modulated PI3K/Akt signaling, elicited cell cycle arrest regulating p27, cyclin-dependent kinase (CDK) protein and cyclin D1, and ultimately induced apoptosis through extrinsic and mitochondria-related pathways in breast cancer cells." (PMID 25338206, 2014). "A study by the Kaelin group in 2009 demonstrated a critical role for this protein in the regulation of the levels of cyclin D1 in breast cancer cell lines." (PMID 24858415, 2014). "Estrogen receptor (ER)-positive breast cancers generally exhibit deregulation of the kinase components CDK4/6 as a result of aberrant cyclin D1 expression or amplification." (PMID 25223380, 2014). "Cyclin D1 is a prominent target of estrogens in breast cancer cells and its induction is important for the progression of cells through the G1 phase of the cell cycle." (PMID 25009600, 2014). "In breast cancer cells, the cell cycle is controlled through a cyclin D1-miR-17/20 auto-regulatory feedback loop." (PMID 24658544, 2014).
breast cancer (continued). "For example, SRC3 is able to increase cyclin D1 expression and activate the Akt signaling way to promote the proliferation and survival of breast cancer cells." (PMID 24626603, 2014). "On the other hand, ATF3 induces DNA synthesis and expression of cyclin D1 in hepatocellular carcinoma cells and enhances cancer cell-initiating features in breast cancer." (PMID 25338635, 2014). "Cyclin D1 expression is increased in certain breast cancer patients as GSK-3beta regulates cyclin D1 turnover." (PMID 24931005, 2014). "The expression of Bmi1 and its correlation with ERα, PR, Ki-67, HER2, p16INK4a, cyclin D1 and pRB was evaluated by immunohistochemistry in a collection of 92 cases of breast cancer and statistically analyzed." (PMID 24559156, 2014). "The ERα-coupled Bmi1 regulatory pathway was subsequently evaluated with regard to its down-stream genes such as p16INK4a and cyclin D1 and clinic-pathological features in breast cancer." (PMID 24559156, 2014). "Results of this study point out AL10 as another cyclin D1-degrading agent for breast cancer treatment." (PMID 24915301, 2014). "On the other hand, proliferation stimulation was observed in hepatocytes, in which AnxA1 was related to EGF, and in breast cancer; in the latter, it was associated with formyl peptide receptor (FPR2) binding and increased levels of cyclin D1." (PMID 24719523, 2014). "Immunoblot analysis was conducted to determine the expression of molecular markers for male breast cancer, including Bcl-2, caspase-3, survivin, and cyclin D1." (PMID 23755153, 2014). "Sox2, together with the Wnt downstream mediator β-catenin, was shown to directly regulate the promoter of Ccnd1 in breast cancer cells, and we show that the iSox2 positive cells were expressing Pph3 and cyclinD1." (PMID 25210856, 2014). "Our results showed that expression of TBLR1 in human breast cancer cells was positively correlated with expression of cyclin D1 and nuclear β-catenin, and activation of genes downstream of β-catenin." (PMID 25341494, 2014). "In vitro studies have demonstrated that in human breast cancer cells AhR, cyclin D1 and cyclin dependent kinase 4 (CDK4) interact within the cell cycle and the interaction was disrupted upon TCDD treatment." (PMID 24755659, 2014). "Cyclin D1 is responsible for cell cycle progression in the transition from G0/G1 to S phase and is overexpressed in parathyroid adenoma, centrocytic lymphoma, breast cancer, squamous cell carcinoma, and esophageal carcinoma." (PMID 25229241, 2014). "The deletion of DS domain abolished the repression of Cyclin D1 in breast cancer and the overexpression of DS domain alone substituted DACH1 to repress S phase entry in breast cancer cells." (PMID 25322986, 2014). "In this study, we observed that the aberrant expression of Vav1 correlated well with the production of Cyclin D1, a critical mediator of estrogen-stimulated cell cycle progression, thus contributing to the proliferation of breast cancer cells." (PMID 24905577, 2014). "The miR-17/20 cluster is known to inhibit breast cancer cellular proliferation through G1/S cell cycle arrest via binding to the cyclin D1 3'UTR." (PMID 24658544, 2014). "Upregulation of cyclin D1 has been shown to shorten the G1 phase and reported to link to the development and progression of many types of cancer, such as breast cancer, gastric cancer and mantle cell lymphoma." (PMID 25355139, 2014).
breast cancer (continued). "Given diverse mechanisms of carcinogenesis in distinct subtypes of breast cancer, we analyzed linkage among CCND1 A870G genotypes with age-related and clinicopathologic characteristics of breast cancer patients." (PMID 25520916, 2014). "A large number of genes were predicted as targets of the selected miRNAs, including many well-known genes that are deregulated in breast cancer, such as CCND1, BCL2, E2F3 and PTEN." (PMID 24788655, 2014). "The high or moderate expressions of breast cancer markers (VEGF, c-Myc and cyclin D1) in mammary cancer tissue change at different stages." (PMID 25230850, 2014). "In breast cancer studies, statistically significant associations have been found between PTEN and cyclin D1 expression patterns." (PMID 25202365, 2014). "(-)-Oleocanthal treatment was shown to reduce expression of cyclin D1 and CDK6, and caused a corresponding increase in p21 and p27 levels in MDA-MB-231 breast cancer cells." (PMID 24849787, 2014). "Knockdown of PLAC1 in breast cancer cells not only blocks cell cycle and proliferation, but also impairs cell motility, migration and invasion probably through inhibiting the cyclin D1 and the phosphorylation of AKT kinase." (PMID 24912876, 2014). "Remarkably, these phenomena seem to be recapitulated in the model with loss of ER and PR and weak expression of Her2/neu and overexpression of cyclin D1, suggesting a common pathway to malignancy between mammary cancers in mouse and human." (PMID 25230850, 2014). "The miR-195/497 cluster also functioned as a tumor suppressor by targeting RAF1/CCND1 in breast cancer." (PMID 24520312, 2014). "Using breast cancer cell lines, studies showed that Erk5 plays roles in cell proliferation by regulating cyclin D1 and CDKs, epithelial mesenchymal transition, MET/HGF-induced migration and integrin/FAK-mediated metastasis." (PMID 24762669, 2014). "Chromatin immunoprecipitation with a flag antibody and PCR amplified human cyclin D1 promoter sequence supported a model that DACH1 was recruited into cyclin D1 promoter context at AP-1 site, as previously observed in human breast cancer." (PMID 25322986, 2014). "It is known that the inhibitory actions of antiestrogens on breast cancer are in part exerted through the downregulation of CCND1." (PMID 24678876, 2014). "This study also demonstrates a positive relationship between ERα-Bmi1 and cyclin D1 in ERα-positive breast cancer." (PMID 24559156, 2014). "TBLR1 plays a key role in the development and progression of breast cancer cells via cyclin D1-transactivation and activation of the β-catenin signaling pathway." (PMID 25341494, 2014). "Cyclin D1 (coded by CCND1) plays first gatekeeper in the cell cycle, whereas copy number alterations of CCND1 were reported as differentially more frequent in triple negative breast cancer samples than those in other breast cancers." (PMID 25520916, 2014). "Our study investigates changes in the chromatin environment at the Cyclin D1 gene (CCND1) during transcriptional initiation in response to estradiol in estrogen receptor positive mammary tumour cells." (PMID 23637611, 2013). "Leptin, collagen VI, and IGF proteins have all been reported to stimulate increases in the transcription and expression of CCND1 (also known as Cyclin D1) in ER expressing breast cancer cells." (PMID 24171117, 2013). "Amplification and/or overexpression of cyclin D1 have been correlated to poor prognosis in breast cancer patients." (PMID 23282137, 2013). "Investigating the expression of both cell regulatory proteins (cyclin D1 and PCNA) demonstrated that there were significant decreases in both PCNA and cyclin D1 expression as a result of RAGE siRNA knockdown in all of the investigated breast cancer cell lines." (PMID 23579957, 2013).
breast cancer (continued). "Specifically, 53% PR+ and 58% ER+ breast cancer patients overexpress cyclin D1, while a smaller, but significant fraction of ER- and PR- breast cancers (21% and 31% respectively) overexpress cyclin D1." (PMID 23886499, 2013). "NF-κB has been demonstrated to regulate many genes including cyclin D1 and c-Myc, and play important roles in tumorigenesis, cell proliferation and metastasis in cancers such as colon, lung and breast cancer." (PMID 23776433, 2013). "Collectively, these results indicated that TGFβ stimulates the formation of a complex between cyclin D1 and p21 in triple negative basal-like breast cancer cells." (PMID 23786849, 2013). "Third, eugenol down-regulated several onco-proteins known to be highly expressed in breast cancer cells and tissues, such as NF-κB, β-catenin, cyclin D1, Bcl-2 and survivin." (PMID 24330704, 2013). "The level of cyclin D1 expression was chosen as a marker of cell proliferation, as it is commonly over-expressed in breast cancer cells." (PMID 24152862, 2013). "The positive correlation of the co-expression of SOX2 and CCND1 with tumorigenesis has also been demonstrated in clinical breast cancer samples." (PMID 24355041, 2013). "ADPs incorporated into nanoparticles down regulated the anti-apoptotic protein, survivin, and cyclin D1 when incubated at low concentrations with breast cancer cell lines." (PMID 23516601, 2013). "The material consisted of 102 formalin-fixed human breast cancer samples, in which cyclin D1, CDK4 and p16 expression was evaluated immunohistochemically." (PMID 23336272, 2013). "This prompted us to investigate the role of the cyclin D1/p21 signaling axis downstream of transforming growth factor beta (TGFβ) in breast cancer progression." (PMID 23786849, 2013). "A recent census concluded that cyclin D1 gene amplification and overexpression are present in breast cancer, lung cancer, melanoma and oral squamous cell carcinomas." (PMID 24499623, 2013). "The inhibition of STAT3 by LLL12 also down-regulated the expression of known STAT3 target genes in ALDH+ breast cancer cells related to cancer cell proliferation, survival, and angiogenesis, including Cyclin D1, survivin, Bcl-2, Bcl-XL, MMP-2, and MMP-9." (PMID 24376586, 2013). "Cyclin D1, one of the protein mediators of the G1/ S cell-cycle transition, is commonly altered in breast cancer and contributes to tumorigenesis, presumably by increasing proliferation." (PMID 23327593, 2013). "CCND1 transcription is stimulated by 17β-estradiol (E2), inhibited by antiestrogens and cell cycle regulated in ERα-positive breast cancer cells." (PMID 23637611, 2013). "Cyclin D1 inversely correlated with miR-17-5p/miR-20a levels in breast cancer samples and cell lines." (PMID 24013378, 2013). "TGFβ induced the expression of p21 in a similar temporal expression pattern as cyclin D1 in these breast cancer cells." (PMID 23786849, 2013). "Cyclin D1 is one of highly over-expressed proteins in breast cancer cells and over-expression of Cyclin D1 protein was found in 40-90% of cases of invasive breast cancer." (PMID 24289849, 2013). "Because cyclin D1 is involved in promoting progression through the cell cycle, these results are also supportive of our data demonstrating a significant difference in breast cancer cell growth following Ob sera exposure." (PMID 23880059, 2013). "Over expression or amplification of cyclin D1 (CCND1) is observed in as many as 50% of breast cancers, wherein it is believed to drive aberrant phosphorylation or inactivation of RB protein." (PMID 23401782, 2013). "In breast cancer, it was reported that cyclin D1 interacted with the FLNa protein to affect the migration and invasion potential of breast cancer cells." (PMID 24137390, 2013). "In this study, we investigated the function of cyclin D1 on breast tumor progression induced by TGFβ, a potent tumor-promoting factor, in metastatic breast cancer cell lines." (PMID 23786849, 2013).